CD4 (CD4 molecule)
Diseases named in the same sentence as CD4 in open-access papers (continued):
Sharing a sentence is not in itself a finding about the gene and the disease.
melanoma (continued). "Tremelimumab, on the other hand, rapidly restores effector and memory CD4 + and CD8 + T-cell pools and T-cell receptor (TCR)-dependent T-cell proliferation in patients with advanced melanoma combined with severe lymphopenia." (PMID 39141277, 2025). "An analysis of clinical databases also revealed that increased LFA-1/ICAM-mediated interactions between CD4+ and CD8+ T cells were correlated with favorable clinical outcomes in patients with melanoma." (PMID 40277945, 2025). "Our results demonstrate that nNOS inhibitor treatment prevented T cells from melanoma-induced immunosuppression, as indicated by significant increases in IL-2+ cells in the CD3+ and CD4+ T cell populations." (PMID 40574005, 2025). "Activation of CD4 + and CD8 + T cells in adaptive immunity is essential for lifelong remission of melanoma." (PMID 40652057, 2025). "This was substantiated by immunostaining for TUNEL, CD4, CD8, CD3, CD206, and CD86 in a melanoma syngeneic tumour model." (PMID 41044178, 2025). "They engineered TRAMPC1 prostate and B16F10 melanoma cells to express GPs and employed the I-AbGP66 tetramer and SMARTA transgenic system to track antigen-specific CD4+ T-cell responses." (PMID 40634636, 2025). "Flow cytometry analysis confirmed significantly higher percentages of PD-1-expressing CD4 and CD8 T cells in melanoma tumors from mice exposed to the combo DAC/IL-33 treatment, but not from those receiving single treatments, with respect to untreated animals." (PMID 40317004, 2025). "A landmark study demonstrated that personalized neoantigen vaccines induced strong CD4+ and CD8+ T-cell responses in patients with melanoma, some of which were durable and polyfunctional." (PMID 41012105, 2025). "It has further been demonstrated that both CD4+ and CD8+ T cells found in the PBMCs and tumor-infiltrating lymphocytes (TILs) of melanoma patients are capable of capturing melanoma antigens, leading to enhanced tumor-specific reactivity and cytotoxicity." (PMID 41181711, 2025). "In fact, in a mouse melanoma model, treatment with a small molecule inhibitor of CAIX increased frequency of effector TH1 skewed CD4+ T cells and increased the response of these tumors to immune checkpoint therapy with anti-PD-1 and anti-CTLA-4 antibodies." (PMID 38510243, 2024). "Activated LCs ingest and process the resultant cell debris; migrate to the draining lymph nodes; and prime melanocyte/melanoma-specific cytotoxic CD8+ T cells, CD4+ helper T cells and B cells." (PMID 38672543, 2024). "A significant portion (40-50%) of malignant melanoma arises from immune-related antigens, such as T cell-granulocyte expression of PD-1, CD8+, CD4+ T, and NK T lymphocyte-granulocytes." (PMID 38233802, 2024). "Several groups have shown the role of increased CD4+ populations in long-term survivors in studies of 4T1 TNBC, B16F10 melanoma, and CT26 colon cancer mouse models, which is in agreement with our results." (PMID 39204325, 2024). "Flot2CD4 mice also showed elevated populations of CD4+ and CD8+ TILs, as well as increased Ki67+ proliferating effector CD4+ and CD8+ cells in the B16F10 melanoma model." (PMID 39499901, 2024). "Overall, CD4+ and CD8+ T cells were seen in small but sparsely distributed clusters closer to the skin epidermis of the primary melanoma tumors, and Foxp3+ T cells showed a more homogeneous distribution within the tumor core irrespective of genotype." (PMID 38327091, 2024). "For example, in a retrospective analysis of melanoma patients, the immune infiltrates in skin tissues consisted of CD3+ lymphocytes with a predominance of CD4+ T cells compared to CD8+ T cells, whilst Foxp3 Treg cells were invariably present." (PMID 39247203, 2024). "have found that in the melanoma model mice treated with CHA, the proportion of M2-TAMs and CD4-Foxp3+ T cells is significantly decreased, while the proportion and activity of CD8+ T cells and M1-TAMs are markedly increased." (PMID 39867913, 2024).
melanoma (continued). "In a melanoma dataset, GBP1 was rarely expressed in tumor cells, whereas it was comparably enriched in macrophages, as well as CD8+ T, CD4+ T, NK, and endothelial cells." (PMID 38758367, 2024). "In melanoma research, scRNA-seq technology has aided in identifying various T cell subsets, such as CD8+ T cells, CD4+ T cells, Tregs, and NK cells are essential in the antitumor immune response." (PMID 39026661, 2024). "Metacluster C58748 represented CD4+CD45RO+ T cells that expressed CCR6, CCR7, CXCR3 and CXCR5 suggesting TFH cells in melanoma which exhibit elevated CEACAM1 levels in the context of treatment-resistant compared to treatment-naive disease." (PMID 38956268, 2024). "HER2 expression significantly reduces the infiltration of immune cells, including CD4+ and CD8+ T cells, in mouse melanoma." (PMID 39313575, 2024). "It is worth mentioning that it was reported that CD4+ and CD8+ T-cell levels in paired tumor and blood samples were inversely correlated in patients with melanoma." (PMID 39113621, 2024). "In another study, it was established that melanomas with a high density of CD3 and CD4 positive lymphocytes had a positive prognosis for survival." (PMID 39199634, 2024). "Together, these studies support a role for CEACAM1 in the function of CD4+ Treg, TFH and Th2-related cells within the melanoma TME." (PMID 38956268, 2024). "The melanoma-bearing Id2fl/flCd4-Cre+ mice had a dramatically decreased frequency of tumor-infiltrating CD8+ T cells, but the frequency of CD4+ T cells was normal." (PMID 38287103, 2024). "This resulted in an increase in CD4+ and CD8+ to 4PD-1hi ratios in the cryoablation plus ipilimumab plus nivolumab cohort at all time points and in the UC and melanoma cohorts at later time points (e.g., 6 weeks post-treatment [PS])." (PMID 38333710, 2024). "BRAF-mutant melanomas exhibit fewer CD8+ T cells and more B cells and CD4+ T cells than BRAF wild-type tumors." (PMID 39582535, 2024). "Flow cytometry data confirmed the significant reduction of CD4+ and CD8+ T cell population in advanced stage tumors compared to early stage D4M melanoma tumors." (PMID 39457009, 2024). "SFI enhances the immunological milieu of melanoma tumors by lowering MDSC and Treg and enhancing CD8+ T cell and CD4+ T cell through fatty acid metabolism." (PMID 39660124, 2024). "In one study, including 68 patients with advanced melanoma treated with anti-CTLA-4 or anti-PD-1, the median level of circulating DNT decreased, while CD4+ and NK cells increased in patients who responded to treatment compared to those who did not." (PMID 39273452, 2024). "Activation of STING-TBK1-Zyxin signaling was evident in B16-F10 melanoma (Fig. EV6A), and phospho-Zyxin induced upon cGAMP administration were mainly in F4/80+ macrophages and, to a lesser extent, in CD4+ T cells (Fig. EV6B,C)." (PMID 39304793, 2024). "Our nanovaccine elicits immune responses from both CD4+ and CD8+ T cells and demonstrates excellent preventive effects against melanoma." (PMID 38764014, 2024). "The nanovaccine elicited CD4+ and CD8+ T cell-based immune responses, demonstrating the potential for melanoma prevention." (PMID 38764014, 2024). "Then, inhibition of Vps34 kinase activity was shown to enhance PD-L1 expression in melanoma and colorectal cancers as well as PD-1 on CD45+ tumor-infiltrating cells (NK cells and both CD8+ and CD4+ T cells)." (PMID 38071322, 2023). "Analysis revealed that XBP1ΔcDC1IRE1trunc-cDC1 mice showed normal B16ChOVA melanoma tumor growth, and normal CD8+/CD4+ T cell tumor infiltration and function compared to control littermates, and a modest decrease in TNF+ CD8+ T cells." (PMID 37346037, 2023). "In fact, this has been demonstrated by a recent preclinical study in which mice with different tumor transplants, including melanoma, received adoptive therapy with chimeric antigen receptor (CAR)-modified CD4+ T cells." (PMID 37965314, 2023).
melanoma (continued). "Via this strategy, MHC Class II-restricted CD4+ CTL were detected ex vivo not only in tumors but also in tumor-infiltrated lymph nodes and peripheral blood of melanoma patients." (PMID 37965314, 2023). "Next, we use mIHC technology to explore the relationship between ITAGAL and CD4+ and CD8+T cells in immune infiltrates in melanoma." (PMID 37388230, 2023). "Here, we report that dietary l-fuc can regulate the biology and interactions between CD4+ T and melanoma cells via cell surface stabilization of an MHC-II protein, which robustly induces itICs and anti-melanoma immunity." (PMID 36690875, 2023). "Studies have reported that the infiltration of T cells, especially CD4+ T cells and CD8+ T cells, into the tumor microenvironment (TME) demonstrate a good prognosis in cancers, such as breast, lung, melanoma, colorectal, brain, and cervical cancer." (PMID 36979847, 2023). "In-depth analysis of immune cells by t-SNE identified CD3+ T cells, CD3+ CD4+ T cells, CD3+ CD8+ T cells and NK cells clusters, moreover, these clusters were decreased in melanoma-beared RNF8−/− mice." (PMID 37391451, 2023). "In a melanoma model treated with adoptive cell transfer (ACT), Th1 cytotoxic T cells differentiated from naïve CD4+ T cells secreted granzyme B, perforin and IFN‐γ, and expressed the transcription factor T‐bet." (PMID 37829505, 2023). "CD4+ and CD8+ T-cells are considered the primary effectors of the anti-tumor response, but in the setting of melanoma, they often enter an anergic and exhausted state." (PMID 37626741, 2023). "Vaccination with LTS220A-UNITETM DNA vaccine (ITI-3000) induced antigen-specific CD4 T cell responses and a strong humoral response that were sufficient to delay tumor growth of a B16F10 melanoma line expressing LTS220A." (PMID 37711623, 2023). "Beyond pre-treatment TME composition, several early modifications of the TME induced by ICIs, such as proliferation of CD4+ and CD8+ T-Cells and NK cells, have been shown in responders with melanoma and NSCLC." (PMID 37046629, 2023). "Other changes observed in melanoma-bearing sentinel LN include (i) reduced CD69+CD8+T cell/Treg cell ratio, (ii) high PD-1 expression on CD4+T and CD8+T cells, and (iii) high CTLA-4 expression on γδ T cells." (PMID 38065972, 2023). "Then, B16-F0 melanoma cells were inoculated subcutaneously and treated with anti-mouse CD8/CD4 antibodies to deplete CD8+ or CD4+ T cells, followed by anti-PD-1, butyrate, or combination treatment." (PMID 37635362, 2023). "TILs are a polyclonal population, which consists of CD20+ B cells, CD3+ T-cells (CD4+ and CD8+ T-cells), and FOXP3+ regulatory T-cells, whose prognostic role in melanoma is currently under investigation." (PMID 36768737, 2023). "The presence of double positive CD4+ CD8+ T cells was demonstrated in metastatic lesions and lymph nodes of melanoma patients, as well as in other cancer types, but was more rarely described in the peripheral blood." (PMID 37274275, 2023). "To investigate a possible influence of Activin-A on CD8+ T cell infiltration in melanoma patients, we analyzed the expression of CD3, CD4, and CD8 as a proxy of T cell infiltration in the PanCancer Melanoma database." (PMID 38304252, 2023). "Compared with CD4+ T cells in spleen, tumor‐infiltrating CD4+ T cells lost expression levels of TCF‐1 and SLAMF6 in a melanoma model, indicating that tumor‐infiltrating CD4+ T cells seem to be a transitory or terminal exhausted T cells." (PMID 37829505, 2023). "Melanomas of Atg5BECKO mice, compared to those of WT mice, displayed an increased amount of both CD8+ T and CD4+ T‐cells and harbored CD8+ T‐cells with higher expression of the key effector molecule Granzyme B (GrzB)." (PMID 38009521, 2023). "Recombinant human IL-7 has been reported to increase CD4+ and CD8+ T cells in the periphery of cancer patients, while the expression of IL-12 in melanoma patients also increases the infiltration of CD8+ cytotoxic T cells into tumors." (PMID 37835433, 2023).
melanoma (continued). "Tα1 increases the number of tumor-infiltrating CD4+ and CD8+ T cells in melanoma and breast cancer xenograft models due to its role in induction of T cell differentiation, enhancement of IFN-γ and IL-2 production, and downregulation of T cell apoptosis." (PMID 37529610, 2023). "We employed B16 melanoma cells to construct a subcutaneous tumor model in mice, and then evaluated the expression of CD3, CD4, CD8, F4/80, CD11b, and PD1 by flow cytometry." (PMID 37189408, 2023). "In patients with bladder cancer, breast cancer, non-small cell lung cancer (NSCLC), and melanoma treated with anti-CTLA-4 immunotherapy, increased levels of ICOS+CD4+ T cells in tumor tissue and peripheral blood were detected." (PMID 37259155, 2023). "The study demonstrated notable CD4+ and CD8+ T-cell responses specific to tumor antigens, suggesting the potential effectiveness of mRNA-electroporated DC vaccines for treating melanoma." (PMID 37726283, 2023). "According to its role in CD4+ CTL activation, melanoma cell-intrinsic expression of MHC class II molecules has been associated with improved patient prognosis and response to immunotherapy with immune checkpoint blocking antibodies." (PMID 37965314, 2023). "In melanoma lesions, CD39 and CD73 are upregulated on Tregs as well as on activated CD4+ and CD8+T-cells and exosomes." (PMID 37345056, 2023). "Most of the PD-L1 positive expressing tumors have a moderate score of CD4+ TILs and CD8+TILs (5-50% of tumor area) in tumoral melanoma environment cells." (PMID 36836455, 2023). "Of note, CD4+ effector T cells also clustered with MHC-II+ dendritic antigen-presenting cells and macrophages in human melanomas." (PMID 37316667, 2023). "The markers utilized in the conducted study, as defined by Tirosh and colleagues, successfully differentiated between various cell types, including melanoma cell (MLANA, PMEL), T cell (CD2, CD3D, CD3E, CD4, CD8A)." (PMID 37620327, 2023). "CA-170 has completed a phase-I trial for the treatment of patients with lymphoma or advanced solid cancers, including melanoma, (NCT02812875) showing acceptable safety and increased numbers of circulating activated CD4+and CD8+T-cells." (PMID 37345056, 2023). "In melanoma, ICOS is the most expressed costimulatory receptor by tumor-infiltrating lymphocytes (TILs) with ICOS positivity found on regulatory, CD4+, and CD8+ T cells." (PMID 37259155, 2023). "Consistent with roles of HLA-DRB1 in CD4+ T cell activation, our findings demonstrate that HLA-DRB1 is expressed and fucosylated in melanoma and required for l-fuc-triggered CD4+ T cell-mediated itIC induction and melanoma suppression." (PMID 36690875, 2023). "In an study carried out with a Lewis lung carcinoma 3LL cell line and B16 melanoma cell line, heat-stressed tumour cells (HS-TEX) contained CL2, CCL3, CCL4, CCL5 and CCL20 chemokines and were able to attract CD11c( +) DC, CD4( +) and CD8( +) T cells." (PMID 37022605, 2023). "For instance, UMAP plots revealed the expression of NUSAP1 in CD4+T, CD8+T, NK, B, DC, monocyte, and macrophage in melanoma (SKCM_GSE120575), with particularly high expression observed in proliferating T cell (T-proli) (the lower plot)." (PMID 37781040, 2023). "When combined with antigen vaccines containing the melanoma TAAs gp100 or trp-1 and LPS or Poly-IC, IL-2/CD25 increased the frequency of effector and memory gp100-specific Pmel-1 CD8+ or TRP-1-specific TRP-1 CD4+ T cells post adoptive transfer." (PMID 35651800, 2022). "For example, the Gp100 antigen and the mutated triosephosphate isomerase antigen-derived peptides were recognized by specific CD4+ T cells in the context of MHC-II HLA-DR and the cancer testis NY-ESO-1 antigen in the context of HLA-DP4 on melanoma cell lines." (PMID 36139357, 2022). "It has been observed that antigen-specific CD4 and CD8 T cells inhibited the growth of melanoma cells, mainly by inducing IFN-γ cytokines that increase tumor-infiltrating lymphocytes and activating APCs to kill melanoma cells." (PMID 36199130, 2022).
melanoma (continued). "CD4+/CD8+ T-cell ratio also appeared to be strongly predictive of sparta-DabTram benefit, although further validation of this biomarker in melanoma is required, while features such as baseline ctDNA shedding and T-cell inflammation were prognostic." (PMID 35728875, 2022). "Among various adjuvants, flagellin is known as an adjuvant for immunotherapy that can induce increases of CD4 + and CD8 T + cells for various cancers including melanoma, colon, and breast cancers." (PMID 36109710, 2022). "NLRC4 is critical for cytokine production in TAM and necessary for the generation of IFN-γ-producing CD4+ and CD8+ T cells in an inflammasome-independent manner, suppressing tumor growth in a subcutaneous murine model of melanoma." (PMID 35739593, 2022). "Consistently, immune cells, such as activated CD4+ T cell and memory B cell, were more abundant in FGFR mutant melanoma." (PMID 36426352, 2022). "Clinically, VLP-based vaccines against TAA Melan-A have been tested in melanoma patients showing Melan-A/Mart-A specific CD8+ and CD4+ responses in the majority of patients with sustained immune responses lasting more than a year." (PMID 35406595, 2022). "These CD4+ T cells were also cytotoxic against an autologous antigen-expressing and MHC-II-positive melanoma cell line in one patient, and blockade of MHC-II on the target cells inhibited this cytotoxicity." (PMID 36159781, 2022). "GILT expression upregulated cathepsin D enzymatic activity in two distinct melanoma cell lines, pointing again to a role for GILT in altering the spectrum of functional peptides for class II presentation and CD4+ T cell recognition." (PMID 35162988, 2022). "When melanoma or ovarian cancer cells overexpressing CXCL9 are s.c. injected into mice, the CD4 and CD8 T-cell recruitment and activation are increased and the tumor growth is slowed down." (PMID 36429101, 2022). "A previous study reported increased expression of Ki-67 by CD4+ and CD8+ T cells in patients with melanoma who received anti-CTLA-4 ipilimumab." (PMID 35514996, 2022). "On the other hand, therapy with the anti CTLA-4 monoclonal antibody tremelimumab was shown to restore CD4+ and CD8+ T-cells in 7 of 10 patients with pretreated advanced melanoma and severe lymphopenia." (PMID 35805052, 2022). "We have also confirmed the induction of an antitumor immune response in vaccine and immunotherapy settings, with critical involvement of NK cells, CD4+ and CD8+ T cells, when our vector is used in immunocompetent C57BL/6 mice and B16-F10 mouse melanoma cells." (PMID 35495634, 2022). "Collectively, these results show that CD3+, CD4+, and CD8+ exhibit a higher sensitivity to CAP treatment than melanoma cells as they required lower doses of CAP to see its cytotoxic and anti-proliferative effects." (PMID 35326381, 2022). "In melanoma tumors that responded to anti-CTLA-4, increased numbers of several subsets of CD4+Th1 cells have been observed." (PMID 36435510, 2022). "MHC class II-expressing melanoma cells and breast cancer cells are capable of MHC class II-restricted processing of protein antigens and presentation of peptide epitopes to CD4 T cells." (PMID 35565329, 2022). "To further investigate these factors, we examined the fractions of 10 immune cell types, including B-cells, DCs, M1/M2 macrophages, NK cells, neutrophils, CD4+, CD8+T-cells and Tregs, among the three TMB subgroups of melanomas." (PMID 36389735, 2022). "As for activated CD4+ T memory cells, it is reported that their infiltration correlated with prolonged PFS and OS in melanoma patients." (PMID 36248853, 2022). "In melanoma patients, the ratio of cytotoxic CD8+ T cells versus CD4+Foxp3+ regulatory T cells (Tregs) in the tumor microenvironment is predictive for the disease outcome." (PMID 36426850, 2022).